THBS4 (thrombospondin 4)
Diseases named in the same sentence as THBS4 in open-access papers (continued):
Sharing a sentence is not in itself a finding about the gene and the disease.
Alzheimer disease (2 papers, 2013 to 2018). A progressive, neurodegenerative disease characterized by loss of function and death of nerve cells in several areas of the brain leading to loss of cognitive function such as memory and language. "For instance, rs438042, located near the intron/exon boundary of THBS4 exon 3, is associated with Alzheimer Disease and might be important for splicing, since THBS4 acts in inflammatory responses and synaptogenesis." (PMID 29658973, 2018).
colorectal tumor (2 papers, 2020 to 2023). "Meanwhile, it is also correlated with CRC invasion and metastasis, for example, excessive PDGFRβ signaling leads to oversecretion of THBS4 and proliferative colorectal tumor development." (PMID 37122535, 2023).
coronary artery disease (2 papers, 2005 to 2025). "In addition, a loss of function polymorphism in THBS4 is strongly associated with premature coronary artery disease." (PMID 16138928, 2005).
Duchenne muscular dystrophy (2 papers, 2014 to 2024). Duchenne muscular dystrophy (DMD) is a neuromuscular disease characterized by rapidly progressive muscle weakness and wasting due to degeneration of skeletal, smooth and cardiac muscle. "Thrombospondin-4 overexpression has been shown to mitigate dystrophic disease in mouse models for Duchenne muscular dystrophy (dystrophin deficiency) and limb-girdle muscular dystrophy type 2F (LGMD2F, δ-sarcoglycan deficiency), while deletion of the thrombospondin-4 gene exacerbated the diseases." (PMID 38926599, 2024). "Taken together, our findings suggest that Thbs4 might not have the same disease-protective effect in mouse models of LGMD2E and LAMA2-RD as it was shown to have in mouse models of Duchenne muscular dystrophy and LGMD2F." (PMID 38926599, 2024).
endothelial dysfunction (2 papers, 2012 to 2025). In vascular diseases, endothelial dysfunction is a systemic pathological state of the endothelium (the inner lining of blood vessels) and can be broadly defined as an imbalance between vasodilating and vasoconstricting substances produced by (or acting on) the endothelium. "In this vein, we have shown for the same subgroup of postinfarction patients, risk associations connected with thrombogenesis using the A387P polymorphism of THBS4 (thrombospondin-4); for oxidative stress, a major cause of endothelial dysfunction, the C242T polymorphism of CYBA (p22phox)." (PMID 22991685, 2012).
gastric tumors (2 papers, 2017 to 2019). "In the present study, we observed that gastric tumors (especially the stromal cells in tumor microenvironment) also express THBS4." (PMID 31703077, 2019).
lymph node metastasis (2 papers, 2019 to 2025). "In present study, we showed in the results that THBS4-high expression in stroma was significantly associated with higher αSMA expression, higher tumor invasion, lymph node metastasis, lymphatic invasion, peritoneal cytology, and peritoneal metastasis." (PMID 31703077, 2019). "This study’s findings indicate that THBS4 could be a potential biomarker for predicting the risk of lymph node metastasis in papillary thyroid microcarcinoma, thus potentially guiding more personalized surgical interventions." (PMID 40303998, 2025). "We therefore propose THBS4 as a promising marker gene for predicting lymph node metastasis and for guiding surgical strategies, yet the precise mechanisms by which it influences PTMC behavior remain unclear." (PMID 40303998, 2025). "Our results suggest THBS4 may serve as a molecular marker for predicting lymph node metastasis in PTMC." (PMID 40303998, 2025). "The multivariate analysis revealed that THBS4 expression, age ≥65 years, macroscopic type 4 (p<0.001), lymph node metastasis (p<0.001), cytology-positive status (p<0.001), peritoneal metastasis (p<0.001), and hepatic metastasis (p<0.001) were independent prognostic factors." (PMID 31703077, 2019). "However, the prognosis of patients with lymph node metastasis which was significantly correlated with THBS4-high might be improved." (PMID 31703077, 2019). "Future studies should validate these findings in larger cohorts and explore the predictive value of THBS4 and PDGFRA as biomarkers of PTMC lymph node metastasis." (PMID 40303998, 2025). "Our study demonstrates the potential clinical utility of using THBS4 and PDGFRA as biomarkers to predict PTMC lymph node metastasis." (PMID 40303998, 2025). "After performing further screening we found that thrombospondin-4 (THBS4) and its corresponding proteins were associated with whether PTMC developed lymph node metastasis or not." (PMID 40303998, 2025).
melanoma (2 papers, 2011 to 2022). A malignant, usually aggressive tumor composed of atypical, neoplastic melanocytes. "We successfully separated the TCGA-melanoma samples into two subtypes on the basis of the expression of the ICD-related genes and developed a prognostic ICDRS involving 3 genes (i.e., GBP2, THBS4, and APOBEC3G) based on the DEGs between the two subtypes." (PMID 36211436, 2022). "Some of these genes had already been described in earlier studies as being down-regulated during melanoma progression: COL17A1, DSC3, KLK7, SLPI and KLK8, or over-expressed, e.g. CCL20, THBS1 and THBS4." (PMID 22032772, 2011).
multiple sclerosis (2 papers, 2020 to 2024). A progressive autoimmune disorder affecting the central nervous system resulting in demyelination. "THBS4 that we found to be downregulated in inactive multiple sclerosis lesions is an adhesive glycoprotein involved in cell-to-cell and cell-to-matrix interactions." (PMID 32272486, 2020).
rheumatoid arthritis (2 papers, 2015 to 2021). A chronic, systemic autoimmune disorder characterized by inflammation in the synovial membranes and articular surfaces. "To address the question, if Thbs4-deficiency would affect the severity of joint destruction in a mouse model of rheumatoid arthritis, we additionally crossed Thbs4-deficient mice with mice carrying a transgene causing over-expression of human TNFα." (PMID 26629997, 2015). "We additionally crossed the Thbs4-deficiency into a TNF-transgenic background, which is commonly used to study the impact of specific molecules on the severity of rheumatoid arthritis." (PMID 26629997, 2015).
type 2 diabetes (2 papers, 2020 to 2021). "Consistently, a recent study observed higher peripheral THBS4 levels in patients with type 2 diabetes." (PMID 35116003, 2021).
adenoma (1 paper, 2010). A neoplasm arising from the epithelium. "THBS4 methylation was detectable in normal mucosal biopsies where it correlated with increasing patient age and negatively with the occurrence of adenomas elsewhere in the colon." (PMID 20846368, 2010). "THBS4 methylation is detectable in normal colonic mucosa and its level may be a biomarker for the occurrence of adenomas and carcinoma." (PMID 20846368, 2010).
anaplastic thyroid cancer (1 paper, 2016). "Reinforcing our observations regarding the relationship of LETM1 with cellular growth signaling, LETM1 silencing resulted in decreased protein levels of PDGFB and mRNA expression of PDGFB, PDGFBR and THBS4 in BCPAP cells and 8505C cells (human anaplastic thyroid cancer cell line)." (PMID 27556512, 2016).
aneurysm (1 paper, 2023). Bulging or ballooning in an area of an artery secondary to arterial wall weakening. "THBS4 conventional knockout mice treated with Ang II showed higher incidence of aneurysm compared with control mice." (PMID 37079380, 2023).
Arthritis (1 paper, 2012). Inflammation of a joint. "Although thrombospondin 4 (THSB4) has not yet been associated with arthritis, thrombospondin 1 (THBS1) is over-expressed in RA tissue." (PMID 23259760, 2012).
Atrophy (1 paper, 2021). Any weakening or degeneration, especially through lack of use. "Here we show that Thbs1, but not Thbs2, Thbs3 or Thbs4, induces lethal cardiac atrophy when overexpressed." (PMID 34168130, 2021).
brain ischemia (1 paper, 2025). Diminished or absent blood supply to the brain caused by obstruction (thrombosis or embolism) of an artery resulting in neurologic damage. "Thbs4-positive cells derive from type B neural stem cells (NSCs) in the subventricular zone (SVZ) after brain ischemia." (PMID 40827993, 2025). "In fact, homozygotic deletion of the Thbs4 gene led to abnormal glial scar formation and increased microvascular hemorrhage following brain ischemia." (PMID 40827993, 2025). "(G) Quantification of membrane-bound HA showed increased HA along Thbs4-positive membrane after brain ischemia (corpus callosum: pink; infarcted cortex: blue; infarcted striatum: green)." (PMID 40827993, 2025). "Thbs4 expression is upregulated in the subventricular zone (SVZ) after brain ischemia." (PMID 40827993, 2025). "To investigate whether brain ischemia could activate astrogliogenesis in the SVZ, we analyzed cell proliferation and Thbs4 expression in the SVZ after MCAO." (PMID 40827993, 2025).
cervical cancer (1 paper, 2021). A primary or metastatic malignant neoplasm involving the cervix. "miR-5701 inhibits the proliferation of cervical cancer cells and the expression of its target gene THBS4." (PMID 33763302, 2021).
colorectal adenocarcinoma (1 paper, 2020). The most common type of colorectal carcinoma. "SW-48 cells are colorectal adenocarcinoma cells like DLD-1, but do not express THBS4." (PMID 32899998, 2020).
colorectal adenoma (1 paper, 2010). An adenoma that arises from the colon or rectum. "THBS4 methylation was lower in the background mucosa of patients with colorectal adenomas compared to those with normal colonoscopies." (PMID 20846368, 2010).
esophageal cancer (1 paper, 2020). A primary or metastatic malignant neoplasm involving the esophagus. "The results showed that EPHA5, LOC100506136, RGS7, THBS4, SCGB1A1, and DPEP1 were dysregulated between esophageal cancer and normal control in GSE13898 validation dataset (all, P<0.05)." (PMID 32068233, 2020).
Hyperinsulinemia (1 paper, 2021). An increased concentration of insulin in the blood. "Conversely, THBS4-/- mice also showed lower fasting glucose level than wild type and relieved hyperinsulinemia in nutrient challenge." (PMID 35116003, 2021).
Interstitial cardiac fibrosis (1 paper, 2022). A type of myocardial fibrosis characterized by excessive diffuse collagen accumulation concentrated in interstitial spaces. "THBS4+-tdTom+ cells showed focal expansion in line with development of patchy interstitial cardiac fibrosis following TAC." (PMID 35641541, 2022).
interstitial lung disease (1 paper, 2025). A diverse group of lung diseases that affect the lung parenchyma. "THBS4 has been associated with interstitial lung disease, a group of conditions in which MMP-12 is often increased and plays a pro-fibrotic role." (PMID 39794761, 2025).
ischemic cardiomyopathy (1 paper, 2025). Ischemic cardiomyopathy is a cardiomyopathy in which a weakness in the muscle of the heart due to inadequate oxygen delivery to the myocardium with coronary artery disease being the most common cause. "Bulk RNA-seq data from the GSE116250 cohort revealed significant overlap between ischemic cardiomyopathy (ICM)-associated differentially expressed genes (DEGs) and FB3-specific markers (THBS4, NTM, NRK, COL14 A1 upregulated; MGST1 downregulated)." (PMID 40447667, 2025).
joint disorders (1 paper, 2012). "However it is notable that CILP2, like other high-scoring plasma protein markers such as COMP, TNXB, THBS4, SPP1, COL2A1 to name a few, are associated with connective tissue development (cartilage matrix synthesis in the case of CILP2) and bone and joint disorders." (PMID 22558154, 2012).
liver disease (1 paper, 2022). "A biomarker panel consisting of HMMR, NXPH4, PITX1 and THBS4 was defined and validated as an effective serologic diagnostic tool for the detection of HCC patients among liver disease patients through the use of simple ELISAs." (PMID 35456219, 2022).
lobular carcinomas (1 paper, 2007). "Although CDH1 (E-cadherin), a classical member of the cadherin superfamily, was downregulated, THBS4 encoding calcium-binding adhesive glycoprotein, thrombospondin-4, was upregulated in all lobular carcinomas." (PMID 17389037, 2007).
metastatic disease (1 paper, 2021). "In the present study, we analyzed DNA methylation of INA, NHLH2, and THBS4 in normal, tumor, and metastatic renal tissue samples and found tissue-specific hypermethylation associated with the metastatic disease state, adverse clinical parameters, and shorter PFS." (PMID 35008203, 2021). "Methylation of the INA, NHLH2, and THBS4 loci was also measured in a subset of 136–142 primary tumor tissues free of lymph node or distant metastasis and a total of 202 cancer metastatic tissues isolated from 100 renal cell cancer patients suffering from metachronous metastatic disease." (PMID 35008203, 2021).
Myocardial fibrosis (1 paper, 2025). "Gonadectomy in older mice was associated with an increased myocardial fibrosis content and higher gene expression levels of Col1, Col3, Postn, and Thbs4." (PMID 40558497, 2025).
nonsmall-cell lung cancer (1 paper, 2021). "High expression of THBS1 or THBS4 is more sensitive to AZD6244, the inhibitor of MEK1 used to treat NSLC (nonsmall-cell lung cancer)." (PMID 34804159, 2021).
oropharyngeal tumors (1 paper, 2023). "Altogether, these observations show that ΔNp63 expression and a the S100A9/THBS4 predictor define two distinct molecular and prognostic subgroups of HPV-related oropharyngeal tumors and suggest that ΔNp63 may play a role in tumor progression and response to therapy." (PMID 38022675, 2023).
osteoporosis (1 paper, 2019). A condition of reduced bone mass, with decreased cortical thickness and a decrease in the number and size of the trabeculae of cancellous bone (but normal chemical composition), resulting in increased fracture incidence. "The results implied that mRNA CDKN2B,CIDEC,and THBS4 may play key roles in osteoporosis process and development." (PMID 31164921, 2019).
papillary thyroid carcinoma (1 paper, 2025). "In some studies, THBS4 regulates tumor biological behavior by affecting CAF, whereas a similar process has not been intensively investigated in papillary thyroid carcinoma." (PMID 40303998, 2025).
polycystic ovary syndrome (1 paper, 2023). A disorder that manifests as multiple cysts on the ovaries. "Thbs4 is abundant in normal ovary and related to the polycystic ovary syndrome-associated gene Thbs1." (PMID 38031019, 2023).
prostate adenocarcinoma (1 paper, 2021). "Here, we found downregulated methylation of THBS1 in BRCA, THBS2 in KIRC, and THBS4 in PRAD (prostate adenocarcinoma) and LIHC (liver hepatocellular carcinoma)." (PMID 34804159, 2021).
psoriasis (1 paper, 2021). An autoimmune condition characterized by red, well-delineated plaques with silvery scales that are usually on the extensor surfaces and scalp. "Similarly, THBS4 was increased in the hyperproliferative skin of psoriasis patients where no fibrotic changes are present." (PMID 34631719, 2021).
renal carcinoma (1 paper, 2021). A carcinoma arising from the epithelium of the renal parenchyma or the renal pelvis. "Thus, metastasis in RCC is significantly associated with methylation alterations in INA, NHLH2, and THBS4 loci, providing independent information for the potential early detection of aggressive renal cancers as a rationale for stratifying patients to adjuvant therapies." (PMID 35008203, 2021).
skin cutaneous melanoma (1 paper, 2021). "The hot spot mutation X399_splice of THBS4 occurred in two patients with SKCM (skin cutaneous melanoma) and also encodes a truncated protein." (PMID 34804159, 2021).
viral myocarditis (1 paper, 2016). Myocarditis that is caused by an infection with a viral agent. "THBS2 and THBS4 isoforms have been shown to protect ECM adverse remodeling in ageing heart and viral myocarditis induced HF." (PMID 27635260, 2016).
tumor (45 papers, 2010 to 2026). "In this study, the association of BM-MSC-derived THBS4 with the angiogenesis of GC associated with H. pylori infection was observed in vivo, in xenograft tumor models, in CAM assays, and in cultured HUVECs." (PMID 34390328, 2021). "Thrombospondin-4 expression by qPCR is significantly higher in normal tissues than in matched tumour samples, supporting the notion that loss of THBS4 provides a selective growth advantage to cancer cells." (PMID 20846368, 2010). "Forced THBS4 over-expression caused a 50-60% repression of tumour colony growth in all eight cell lines examined compared to control cell lines." (PMID 20846368, 2010). "THBS4 has shown to be methylated in several tumour types, and this methylation is associated with transcriptional down-regulation." (PMID 20846368, 2010). "Expression intensities of SPARC, COL1A1, COL5A1, COMP, IBSP, and THBS4 were interpreted in tumor stroma, as they were associated with ECM-related pathways, and the expression intensity of SORD was interpreted in tumor cells, as it was associated with the EMT pathway." (PMID 34503278, 2021). "There is increasing evidence that THBS4 and PDGFRβ are associated with tumor development." (PMID 32899998, 2020). "Specifically, THBS4 participates in biological processes such as cell proliferation, adhesion, pain signal transduction, and tumor progression, as noted in reference." (PMID 40044042, 2025). "Our study, therefore, centered on tumor-microenvironment interactions, particularly the roles of THBS4 and CAFs." (PMID 40303998, 2025). "According to recent studies, the origin of THBS4 varies in different tumors, either from tumor cells or mesenchymal stromal cells, suggesting heterogeneity of THBS4 expression among tumors." (PMID 40303998, 2025). "In disease contexts, Thbs4 is involved in several tumor-related diseases and mainly expressed in the extracellular matrix surrounding tumor cells, particularly in regions of high cell density and invasiveness." (PMID 41153662, 2025). "Several supermere‐specific proteins, such as THBS4, SDC1 and GPC1, are implicated in tumor progression, cell adhesion and intercellular signaling and have been detected in tumor‐derived EVs in previous studies." (PMID 41039818, 2025). "Consistently, supplementing primary HER2-positive tumor cultures with recombinant SAA1, SAA2, or THBS4 peptides enhanced tumor cell proliferation and migration." (PMID 41387465, 2025). "Consistent with these previous findings, we found that TERT and THBS4 had significantly higher expression levels in tumor than in normal matched samples in all cohorts and that MT1M showed the opposite tendency." (PMID 38985879, 2024). "SFRP2 was identified as a regulator of the TME through its impact on Wnt signaling and tumor angiogenesis, while THBS4 influenced cancer stem cell-like properties in PCa via the PI3K/Akt pathway." (PMID 38672562, 2024). "Previous research has revealed that CAFs activate HSF1 in tumor cells by secreting thrombospondin-4 (TSP-4)." (PMID 38649701, 2024). "Additional studies conducted on these structures, defined specific molecular signatures of tumor tissues containing CS, such as high levels of nitric oxide synthase (iNOS), increased synthesis of thrombospondin 4 and high levels of matrix metalloproteinases." (PMID 37222874, 2023). "In vitro, THBS4 also promotes tumor progression by interacting with ITGB1 via the FAK/PI3K/AKT pathway." (PMID 36241983, 2022). "Survival analysis using available follow-up data for a subset of tumors demonstrated a possible significant association of higher tumor methylation and shortened time to disease progression in univariate log rank analyses for INA, NHLH2, and THBS4 methylation." (PMID 35008203, 2021). "In two recent studies THBS4 promoted cancer progression by enhancing tumor cell migration and invasion." (PMID 34631719, 2021).